EGFR (epidermal growth factor receptor)
Diseases named in the same sentence as EGFR in open-access papers (continued):
Sharing a sentence is not in itself a finding about the gene and the disease.
lung cancer (continued). "Broadening this approach beyond EGFR-mutant lung cancer requires robust methods for estimating ctDNA content, such as the calculation of ctDNA tumor fraction (TF), an algorithmic method that can provide information on ctDNA content even without the detection of pathogenic variants." (PMID 40027147, 2024). "For lung cancer, the miRNAs known and identified by MoPC are miR-7–5p and miR-21–5p (chemosensitive and chemoresistant, respectively) and miR-200c-5p and miR-223–5p with EGFR-TKI and ALK-TKI sensitivity." (PMID 38512819, 2024). "Investigators have shown that the exosomal EGFR and PD-L1, two biomarkers, may be used to diagnose lung cancer using the compact SPR biosensor." (PMID 38816782, 2024). "However, our study revealed that the effect of ICI treatment does not neutralize the short duration of response to EGFR-TKIs, suggesting the importance of long-term response to EGFR-TKIs in terms of survival benefits in patients with EGFR-mutant lung cancer." (PMID 38347279, 2024). "Secondary resistance EGFR mutations, such as T790M with first and second-generation EGFR-TKIs and C797S mutation with third-generation EGFR-TKI, are common causes of acquired resistance to EGFR-TKIs in EGFR-mutant lung cancer." (PMID 38806586, 2024). "Significant progress in lung cancer research has introduced novel treatments, such as epidermal growth factor receptor (EGFR)-targeted therapies, which are advised as the primary treatment for NSCLC with EGFR mutations, with these mutations predominantly manifesting in ADC." (PMID 38672733, 2024). "Therefore, four different cell lines with different EGFR expression levels were employed for cell experiments, including human epidermoid carcinoma (A431), human cervical carcinoma (HeLa), human lung cancer (A549) and mouse embryonic cells (NIH-3T3)." (PMID 39138197, 2024). "Our findings suggest that further investigation of the lipid pathway in BMs of EGFR-mutant lung cancer patients is warranted and that lipid metabolism may be the next potential preventive therapeutic target for LUAD BM." (PMID 38464823, 2024). "Additionally, combining NLR with PD-L1 expression has emerged as a promising marker for predicting lung cancer recurrence post-surgery, particularly in patients with wild-type EGFR." (PMID 39335736, 2024). "Since lung cancer patients harboring EGFR ECD variants are not usually considered as candidates for EGFR TKI therapy, we were unable to find literature reports assessing the effects of EGFR-targeted TKIs in such patients." (PMID 38548752, 2024). "The advent of molecular targeted therapies, particularly those targeting receptor tyrosine kinases in advanced NSCLC (e.g., mutations in the epidermal growth factor receptor [EGFR] or anaplastic lymphoma kinase [ALK] genes), has revolutionized lung cancer treatment." (PMID 39230026, 2024). "We herein report a case of the use of furmonertinib, to treat lung cancer with EGFR exon 20ins." (PMID 39743996, 2024). "One of the major lung cancer biomarkers is the epidermal growth factor receptor (EGFR)." (PMID 39449797, 2024). "By synthesizing these findings, we hope to offer valuable insights into the optimal use of EGFR TKIs and identify potential areas for further research in the pursuit of a better understanding of the molecular genomics that drive lung cancer and more effective therapies for NSCLC patients." (PMID 39518531, 2024). "We next explored whether EGFR specific scFv functionalized exoscFv could efficiently deliver siLPCAT1 across BBB to the BM site of lung cancer in vivo." (PMID 38589859, 2024). "Additionally, lentiviral deletion of DUSP22 by shRNA enhances lung cancer cell migration through EGFR/c-Met and PD-L1-dependent pathways." (PMID 38877005, 2024). "Additionally, a study conducted by Japanese scholars in 2019 compared the treatment sequences of EGFR-positive lung cancer brain metastases patients." (PMID 38434971, 2024).
lung cancer (continued). "In addition, anti-EGFR strategies are being integrated into combination regimens with conventional chemotherapeutics, especially in colorectal cancer and lung carcinoma." (PMID 39033209, 2024). "As per the remaining results, patients with multiple lung cancers, with at least one gene mutation, and those with multiple lung cancers with all EGFR-wildtype tumors did not exhibit different demographic characteristics." (PMID 37124493, 2023). "In fact, a clinical trial is currently in progress using the TUSC2 expression plasmid containing DOTAP:cholesterol nanoparticles (REQORSA) in combination with EGFR inhibitor Osimertinib (NCT04486833) in advanced lung cancer patients who experienced disease progression on Osimertinib alone." (PMID 37173921, 2023). "The combination of antiangiogenic agents with epidermal growth factor receptor inhibitors (EGFR‐TKIs) and chemotherapy with EGFR‐TKIs are the most common combination treatment options in epidermal growth factor receptor (EGFR) positive non‐small cell lung cancer (NSCLC)." (PMID 36594109, 2023). "introduced erlotinib, an EGFR inhibitor commonly used in lung cancer treatment, into organoids culture and observed a significant enrichment of at least one known therapy-resistant mutation (BRAFV600E, KRASG12D, KRASG12V, and PIK3CAH1047R) associated with erlotinib after prolonged culture." (PMID 37941550, 2023). "Thus, our study suggests that AICAR induces lung tumour cell death through increasing DNA damage and cellular apoptosis in EGFR-mutant lung cancer cell lines." (PMID 36810913, 2023). "There has been the number of molecular alterations identified in lung cancer including oncogenes and tumor suppressor genes, such as Epidermal Growth Factor Receptor (EGFR), Anaplastic Lymphoma Kinase (ALK) which have high relative frequencies as molecular targets." (PMID 36990974, 2023). "In addition, KDM5A is necessary to create a transient chromatin state in EGFR-mutant lung cancer cell lines with elevated expression driven by the IGF-1 signalling pathway in both DTPs and drug-tolerant expanded persisters (DTEPs)." (PMID 37569598, 2023). "Collectively, our results reflect that the combination of 8PN and EGFR TKI exerts a strong inhibitory effect on lung cancer cells and might be an effective chemotherapy for lung cancer patients." (PMID 37013960, 2023). "Although several EGFR tyrosine kinase inhibitors (EGFR-TKIs), such as erlotinib (Er), have been developed, acquired resistance to these therapies is a major challenge, limiting their long-term effectiveness for lung cancer." (PMID 37717020, 2023). "Moreover, cynaropicrin exhibited anti-proliferative and apoptotic activities in lung cancer cells through the inactivation of the EGFR/AKT signaling pathway." (PMID 37344563, 2023). "In lung cancer, the EGFR tyrosine kinase inhibitor osimertinib has been administered." (PMID 36830998, 2023). "Approximately 85% of all lung cancers are non-small cell lung cancer (NSCLC).In advanced non-small cell lung cancer (NSCLC), epidermal growth factor receptor (EGFR) mutations are presented in approximately 40% of Asian populations and approximately 10% to 15% in non-Asian populations." (PMID 37840124, 2023). "EGFR tyrosine kinase inhibitors (TKIs) are an important treatment regimen for lung cancer patients." (PMID 38137354, 2023). "However, our study focused only on patients treated with afatinib, and this study was one of the largest studies examining the effectiveness of LCT in patients with advanced lung cancer receiving an EGFR-TKI." (PMID 37046679, 2023). "In addition to the PIK3CA/EGFR co-mutated PC-9-PIK3CA-M and HCC-827-PIK3CA-M cells, we also used H1975 and H1650 lung cancer cells to evaluate the synergetic effects of gefitinib and BYL719." (PMID 37553597, 2023). "We also found that EGFR TKIs enhanced IL6 mRNA expression in CDCP1 knockdown lung cancer cells." (PMID 37013960, 2023).
lung cancer (continued). "Furthermore, TAGLN was mainly expressed in the stromal region in the EGFR-driven spontaneous lung cancer mice." (PMID 36990991, 2023). "For example, tumor-infiltrating lymphocytes were dramatically reduced in EGFR-mutated lung cancer; whereas CD8 + T cells were either absent or functionally impaired in ALK-positive lung cancer." (PMID 38031067, 2023). "In addition, targeting acetylcholine signaling modulates persistent drug resistance in epidermal growth factor receptor (EGFR)-mutant lung cancer and prevents tumor recurrence." (PMID 36770805, 2023). "Therefore, activation of EGFR signaling can be one of the factors that contribute to the enhanced ability to promote tumor growth in PM2.5‐exposed lung cancer cells." (PMID 36975376, 2023). "Lung cancer in non-smokers is associated with mutations in the epidermal growth factor receptor gene (EGFR)." (PMID 37131310, 2023). "KAN0441571C was more effective than erlotinib in inducing apoptosis of lung cancer cells, irrespective of EGFR mutations." (PMID 37111634, 2023). "Our TM‐negative group had greater rates of EGFR mutations (43.4% vs. 26.4%) probably because of the predominance of nonsmokers and adenocarcinoma, as well as early‐stage lung cancer." (PMID 36806719, 2023). "Thus, dually targeting JAK and EGFR with two inhibitors can better treat EGFR-dependent lung cancer." (PMID 36810913, 2023). "A more recent study from 2014 presented additional findings regarding the 225-NP treatment of EGFR-positive lung cancer, indicating that tumoral cells are being arrested in the G2/M phase of the cell cycle and suffer DNA damage, leading to effective tumor growth inhibition both in vitro and in vivo." (PMID 37754880, 2023). "In addition to the EGFR mutation status of ADC, we investigated different types of lung cancer (ADC and SCC) and five subtypes of ADC." (PMID 37407963, 2023). "The purpose of this study was to explore the efficacy and safety of toripalimab combined with anlotinib in patients with advanced non‐small cell lung cancer (NSCLC) who acquired resistance to epidermal growth factor receptor tyrosine kinase inhibitors (EGFR‐TKIs)." (PMID 37723846, 2023). "This suggests that the proposed drugs' phytochemicals structures are likely to be more stable in the EGFR protein pocket, thus enabling them to reach their therapeutic target against breast and lung cancer cell growth with greater efficacy than Tamoxifen and Erlotinib." (PMID 37128337, 2023). "The EGFR driver mutations observed in air-pollution associated ADC in never-smokers, were also far more frequent in women which also appear more likely to develop ADC than SCC and to have a higher risk of developing lung cancer from smoking, compared to men." (PMID 37696458, 2023). "Notably, treatment of lung cancer cells with the EGFR tyrosine kinase inhibitor, gefitinib, or the KRAS-G12C inhibitor, AMG 510, reduced CD47 expression, which is consistent with the newly discovered mechanisms of CD47 regulation by EGFR and KRAS." (PMID 37958404, 2023). "In the present study, we found in lung cancer cells the expression of CNOT3 could be regulated by EGFR signaling pathway and c-Jun, a transcription factor downstream of EGFR, transcriptionally regulated its expression." (PMID 37919290, 2023). "The potential predictive factors in the multivariable analysis to construct a prognostic index included Karnofsky performance status, BM at initial lung cancer diagnosis, BM progression after TKI, EGFR mutation type, uncontrolled primary tumors, and number of BM." (PMID 37020869, 2023). "The emergence of drug resistance remains a major issue for EGFR-TKIs treatment of lung cancer." (PMID 37065830, 2023). "Therefore, the combined use of PPARγ agonists and EGFR TKIs have recently been suggested for the treatment of lung cancer patients." (PMID 37190124, 2023).
lung cancer (continued). "The advent of the prototypic third-generation EGFR TKI, osimertinib, which is highly selective for both activating EGFR and T790M resistance mutations, offers further advantages to non–small cell lung cancer (NSCLC) patients with de novo or acquired T790M mutations." (PMID 36915101, 2023). "A lung cancer patient with EGFR KDD has demonstrated considerable efficacy in Nivolumab treatment." (PMID 36325957, 2023). "EGFR and KRAS are two other frequently mutated genes in lung cancer." (PMID 37696458, 2023). "EGF activates EGFR signaling and promotes lung cancer cell proliferation, invasion, and metastasis." (PMID 37990309, 2023). "The EGFR/ERK signaling pathway plays a key role in lung cancer metastases." (PMID 36766810, 2023). "There are targeted therapies available for patients with advanced lung adenocarcinoma, and the most recent National Comprehensive Cancer Network (NCCN) lung cancer recommendations advocate for further identification of relevant drug targets, including mutant EGFR (19DEL, L858R)." (PMID 37250453, 2023). "It showed that both engineered BaF3 cells harboring EGFRL858R/T790M/C797S or EGFR19del/T790M/C797S were sensitive to HCD3514, as well as the PC-9-OR cells (EGFR19del/T790M/C797S expressing PC-9 lung cancer cells), with enhanced inhibition the phosphorylation of EGFR." (PMID 36605493, 2023). "EGFR signaling activation, such as gene amplification and somatic activating mutations (e.g., L858R and exon 19 deletions), is a major driver of non-small-cell lung cancer (NSCLC), which constitutes more than 85% of all lung cancer cases." (PMID 37813845, 2023). "This indicates that additional mechanisms and properties associated with combustion particle exposure such as PAHs, may be necessary to promote EGFR-driven lung cancers." (PMID 37696458, 2023). "Gefitinib is recommended for EGFR‐positive lung cancer patients with poor PS." (PMID 36578073, 2023). "Furthermore, trametinib has been shown to overcome KRAS-G12V-induced osimertinib resistance in a leptomeningeal carcinomatosis model of EGFR-mutant lung cancer." (PMID 37976123, 2023). "Our index does not contain molecular data such as EGFR mutation status in lung cancer patients, HER2 status in breast cancer patients and BRAF mutation status in melanoma patients." (PMID 37370784, 2023). "In preclinical studies, weekly dosing with a number of EGFR inhibitors, including erlotinib and gefitinib, EGFR inhibitors were equally effective as daily dosing in breast, bladder and colon cancer models, and potentially more effective in two lung cancer models." (PMID 37169023, 2023). "Macrophages have been previously shown to contribute to the progression of EGFR-mutant lung cancer." (PMID 36817465, 2023). "The least predictive value was in lung cancer, which could be related to the higher prevalence of EGFR mutant lung cancer which has an Asian predilection, thus less amenable to PRS developed in Caucasian population." (PMID 36971353, 2023). "In conclusion, we used the state-of-the-art mass spectrometry platforms to characterize the cell surface N-glycome, proteome, and glycan distribution maps of a cohort of Filipino lung cancer samples (n = 5), who were previously characterized clinically for ALK and EGFR mutations." (PMID 36900350, 2023). "In addition, UA hinders the angiogenesis, migration invasion, and tumor sphere formation of lung cancer by binding EGFR, reducing the level of phosphor-EGFR, and inhibiting the JAK/STA3 pathway." (PMID 37089712, 2023). "CUB domain‐containing protein 1 plays a variety of promoting roles in EGFR‐driven lung cancer." (PMID 37013960, 2023). "Our results support the notion that PARP inhibitors administered in combination with immunotherapy using EGFR/Notch bsAbs have broad potential for the treatment of various tumours beyond hereditary BRCA1-deficient and BRCA2-deficient tumours, including lung cancer." (PMID 37441599, 2023).
lung cancer (continued). "Moreover, the knockdown of CDCP1 in lung cancer cells significantly lowered the cell viability upon EGFR TKI treatment compared with TKI treatment alone." (PMID 37013960, 2023). "However, while epidermal growth factorreceptor (EGFR) is an important parameter for lung cancer, EGFR inhibitorsalso show great promise in the treatment of the disease." (PMID 37663500, 2023). "Gefitinib is a tyrosine kinase inhibitor targeting the epidermal growth factor receptor(EGFR)/MAPK, used as a molecularly targeted therapy for EGFR mutation positive lung cancers; it may share the same mechanism as carvedilol on the MARK pathway." (PMID 36765542, 2023). "Moreover, it was revealed that CAF infiltration also contributes to the successful treatment of lung cancer patients due to their role in acquiring resistance to epidermal growth factor receptor tyrosine kinase inhibitors (EGFR)." (PMID 37761972, 2023). "We believe that gefitinib could be an acceptable EGFR-TKI for the treatment of lung cancer patients aged ≥75 years as part of an individualized therapy based on patient values." (PMID 37179737, 2023). "However, a retrospective study showed that the response of PE of lung cancer patients with EGFR mutation and MPE to EGFR-TKIs (including gefitinib, alfatinib and oxitinib) was worse than that of solid malignant tumors." (PMID 36874629, 2023). "Taken together, we demonstrate that by destabilizing ERBB2, we controlled and downregulated YES1 and WNK1 that are well-known causes of drug resistance in ERBB2+ trastuzumab drug-resistant breast cancer and in osimertinib-resistant EGFR T790M lung cancer, respectively." (PMID 37359373, 2023). "Moreover, EGFR inhibition triggers RIG-I-mediated type I IFN response in lung cancer, which, however, contributes to EGFR inhibitor resistance." (PMID 36755342, 2023). "A recent study investigated global expression profiles of miRNAs in never smoker and smoker lung cancer patients with EGFR mutation versus wild type." (PMID 37686122, 2023). "In EGFR mutant lung cancers, elevated MIG6 RNA and protein levels were observed." (PMID 37834326, 2023). "SPP1 enhances the drug resistance of the second generation EGFR TKI in lung cancer treatment." (PMID 36688087, 2023). "Two genes, Kras and EGFR, are the most important for lung cancer formation." (PMID 36918558, 2023). "Additionally, the effect of EGFR tyrosine kinase inhibitors is clearly different between “EGFR-positive” and “EGFR-negative” lung cancer." (PMID 37240498, 2023). "ALK rearrangement, EGFR mutation, and PDL‐1 testing are all recommended as part of molecular testing for metastatic NSCLC by NCCN in light of the significance of directed treatment for the overall control of lung cancer." (PMID 36971312, 2023). "In the real‐world practice, we often use hot spot analysis, such as Roche Cobas V2, rather than an NGS to detect EGFR mutations at both lung cancer diagnosis, and resistance to an EGFR‐TKI." (PMID 38140788, 2023). "CAR-T cells targeting EGFR variant III, mesothelin, Erythropoietin-producing hepatocellular carcinoma A2 (EphA2), Delta-like 3 (DLL3), PSCA- and MUC-1, and PD-L1 have shown significant antitumor effects against lung cancer cells in vitro and in vivo." (PMID 37420216, 2023). "Similarly, MM-121 was also found to induce sensitivity to gefitinib (an EGFR inhibitor) in gefitinib-resistant lung cancer cell lines." (PMID 37947595, 2023). "Our data provided additional evidence for the previous studies, suggesting that EGFR-TKIs may have limited efficacy on multifocal lung cancer, especially for the GGO lesions." (PMID 36611170, 2023). "Tyrosine kinase inhibitors (TKIs) are effective for the treatment of non‐small cell lung cancer (NSCLC) patients with activating mutations of the epidermal growth factor receptor (EGFR), but responses are not durable as tumors develop resistance." (PMID 36621830, 2023). "The anti-EGFR/HER3 BsAb SI-B001 is included in phase 2/3 trials in lung cancer." (PMID 37153618, 2023).